CRP (C-reactive protein)
Diseases named in the same sentence as CRP in open-access papers (continued):
Sharing a sentence is not in itself a finding about the gene and the disease.
COVID-19 (continued). "Moreover, high CRP is linked to severe inflammatory conditions, including major cardiac events and probability of stroke in the COVID-19 patients." (PMID 37365605, 2023). "Interestingly, a positive linear relationship was also observed in their study between cTnT and CRP, indicating an association between the severities of inflammation observed in COVID-19 and myocardial damage." (PMID 37275509, 2023). "Similarly, another study has shown that, during the hyperinflammation stage of COVID-19, pneumonia, which is known to be associated with poor prognosis, as well as inflammatory biomarkers, such as CRP, d-dimer, and ferritin, are significantly elevated." (PMID 37109014, 2023). "Herein, the refractory respiratory failure in patients with COVID-19 was associated with increased CRP, D-dimers, LDH, Ferritin, HMGB1, and IL-33, as well as higher numbers of circulating neutrophils, higher plasma levels of IL-6 and IL-10, and diminished numbers of lymphocytes and platelets." (PMID 37604833, 2023). "We aimed to investigate the association between C-Reactive Protein (CRP) and COVID-19 severity." (PMID 37311846, 2023). "The aim of this retrospective cohort study was to determine whether elevated levels of CRP measured in the early stages of COVID-19 were associated with higher mortality in COVID-19 patients." (PMID 37990060, 2023). "The severity of COVID-19 is associated with the increase in circulating proinflammatory mediators, including interleukin (IL)-6, soluble IL-2 receptor (sIL-2R), C-reactive protein (CRP), and ferritin." (PMID 36835000, 2023). "On the other hand, the Cox regression model showed that, while analyzing additional variables such as age, gender, heart disease, and CRP value, the association between vitamin D concentration and mortality risk in patients with COVID-19 depended on baseline eGFR." (PMID 37727794, 2023). "Indeed, Cu levels have been previously associated with CRP, suggesting an association between serum Cu levels and COVID-19 severity." (PMID 37623875, 2023). "D-dimer, CRP and fibrinogen are also associated with the severity of COVID-19." (PMID 37390087, 2023). "High CRP levels may be linked to an overproduction of inflammatory cytokines in COVID-19 individuals with severe symptoms." (PMID 38024833, 2023). "Their findings indicated that this allele exhibited a tendency not only to be associated with protection against COVID-19 but also with lower levels of C-reactive protein, despite higher ALT and lower albumin levels in severe COVID-19 patients of European ancestry." (PMID 37632067, 2023). "In addition, CRP is also positively correlated with the severity of COVID-19 and associated with the clinical outcomes of the disease." (PMID 37065120, 2023). "In addition, CRP has been associated with disease development and is an early predictor for severe COVID-19." (PMID 37235308, 2023). "Additionally, C-reactive protein, lactate dehydrogenase, and aspartate aminotransferase were significant risk factors associated with COVID-19 mortality." (PMID 36769445, 2023). "Based on this, this study described the profile of laboratory biomarkers of inflammation (CRP and ferritin) and coagulation (D-dimer) associated with COVID-19 in pregnant women hospitalized in a reference maternity hospital in the city of Belém, Pará, northern Brazil." (PMID 37510647, 2023). "For example, eosinophilia in symptomatic COVID-19 patients has been linked to a lower level of inflammatory markers such as high-sensitivity CRP, suggesting a protective role of eosinophils in mitigating the severity of inflammatory diseases through an inhibitory mechanism." (PMID 37483591, 2023). "Besides IL-6 and LDH, other laboratory parameters are cited in the literature as independent risk factors of death in COVID-19, such as neutrophil count, platelet count, CRP, D-dimers, troponin-I and low total testosterone." (PMID 36836679, 2023).
COVID-19 (continued). "Absolute CRP levels have been more predictive of patient outcomes than neutrophil counts or patient age, and CRP levels > 10 mg/dL also have been linked with COVID-19 hyperinflammatory syndrome and subsequent cytokine storm, harbingers of more severe outcomes." (PMID 38003780, 2023). "Therefore, in this study, we evaluated the association between the severity of periodontitis, COVID-19, IL-6, and CRP." (PMID 37568161, 2023). "This analysis revealed that persisting inflammatory parameters, such as CRP, IL-6, d-dimer and ferritin as well as acute COVID-19 severity predicted the risk for persistence of structural lung abnormalities at follow-up, whereas dyslipidemia and dysglycemia did not." (PMID 36788324, 2023). "Also, the observed increases in memory T cells (CD45RO) and CD4 T cells (CD3+ and RO+) were associated with lower CRP levels, potentially leading to COVID-19 recovery and immunity." (PMID 36986336, 2023). "With the exception of the typical classic methods that cannot be performed in non-laboratory facilities, some other point-of-care diagnostic assays are used for CRP and various other biomolecules, and were widely performed even for self-diagnosis purposes during COVID-19 pandemic [1155]." (PMID 37873776, 2023). "As a general indicator of inflammation, CRP is associated with the clinical severity of COVID-19." (PMID 37496884, 2023). "Hence in this study we assessed the prognostic value of high sensitivity C-reactive protein (hs-CRP) for predicting cardiovascular diseases (CVD) risk in COVID-19 survivors." (PMID 37744945, 2023). "As a result, COVID-19 and CRP were found to be independent factors associated with MDW." (PMID 36973757, 2023). "A recent randomized control trial enrolled patients with coronavirus disease 2019 (COVID) and found that tcVNS significantly reduced the levels of inflammatory markers, specifically C-reactive protein (CRP) and procalcitonin." (PMID 37484689, 2023). "CRP, an acute-phase protein, is independently associated with critical illness in COVID-19." (PMID 37900669, 2023). "CRP, a biomarker for chronic inflammation, is an important mortality risk factor for Blacks, as evidenced by the significant association between increased CRP levels and greater risk of both overall and cause-specific deaths due to COVID-19 and digestive cancers." (PMID 36963080, 2023). "Previous studies have revealed that CRP levels were correlated with early lung tissue damage of COVID-19 pneumonia and could be associated with the severity of COVID-19." (PMID 38051999, 2023). "Besides, most studies in recent years have pointed out that for COVID-19 patients, higher CRP concentrations are closely related to higher mortality risk." (PMID 37990060, 2023). "Since both elevated CRP levels and reduced lymphocyte counts are reportedly linked to an adverse prognosis in COVID-19 patients, LCR could potentially exploit the prognostic value of both markers in either a synergistic or additive fashion." (PMID 37373898, 2023). "Similarly, for respiratory rate variables, SpO2, CRP, Ferritin are the factors associated with COVID-19 mortality." (PMID 37916134, 2023). "Indeed, CRP has been demonstrated to have good diagnostic accuracy in the early prediction of severe COVID-19 patients with sensitivity and specificity of 83% and 91% respectively." (PMID 38057707, 2023). "High mortality in COVID-19 is also associated with elevated levels of CRP and PTC in blood serum." (PMID 36900724, 2023). "Several inflammatory conditions have been linked with COVID-19, including activation of macrophages, hematological dysfunctions, and cytokinaemia or cytokine storm, defined by upregulation of C-reactive protein (CRP), interleukins (IL), and tumor necrosis factor-alpha (TNF-α)." (PMID 37008057, 2023). "In COVID-19 patients, the increase in CRP is associated with the severity of the disease." (PMID 36788868, 2023).
COVID-19 (continued). "Elevated TnT, CRP, and D-dimer, and declined PaO2/FiO2 suggest that fatality due to COVID-19 was associated with multiple organ dysfunction studies show other coagulation parameters such as PT, PTT, and fibrinogen in non-ICU-patients were less significant in identifying patients needing ICU care." (PMID 37942197, 2023). "The combined use of FLR and CRP for risk-stratifying COVID-19 patients deserves further validation." (PMID 37893192, 2023). "Additionally, comorbidities such as older age (>65), hypertension, taking medications, and CRP (>33.55 mg/L) are considered risk factors that are more likely to contribute to kidney impairment in COVID-19 positive patients." (PMID 36819137, 2023). "Moreover, our data reaffirm previous findings that inflammatory biomarkers, including CRP, procalcitonin, and ferritin, are associated with severe disease and pneumonia because COVID-19 causes a cytokine storm and systemic inflammation with severe disease." (PMID 37798709, 2023). "In this sense, the mortality caused by COVID-19 could be inferred considering not only hematological determinations, but also inflammatory biomarkers such as C-reactive protein, as shown in the mortality model proposed in the current analysis." (PMID 35806866, 2022). "A similar association between CRP levels with the early stage of COVID-19 was also noted by Wang." (PMID 35455363, 2022). "The results of recent systematic reviews, comprised of more than 10,000 COVID-19 patients, confirmed the association of high levels of CRP with COVID19 severity, suggesting that COVID19 cases should be screened regularly for CRP levels to closely monitor disease severity and disease progression." (PMID 36583110, 2022). "Furthermore, this study incorporates C-reactive protein (CRP) and D-dimer levels, which play a crucial role in assessing the severity of COVID-19, as their elevated levels are associated with a poor prognosis." (PMID 35381033, 2022). "Additionally, we found an indirect path between SE and teachers’ perception about the impact of COVID-19 through teachers’ perception of risk of contracting SARS-CoV-2 (CRP) and perception of the effectiveness of health measures (PEHM) (β = 0.03; p < 0.001)." (PMID 36141916, 2022). "Together with increased CATi, dyslipidemia and increased CRP were also associated to unfavorable outcome in diabetic patients suggesting a conundrum of metabolic and inflammatory pathways playing a central role in the severity of COVID-19 in diabetic patients." (PMID 36587209, 2022). "C-reactive protein (CRP) is an acute phase reactant protein that is increased in response to inflammation, simultaneously with a boost of other inflammatory cytokines associated with severity and mortality of COVID-19 patients." (PMID 35281265, 2022). "This could be attributed to the cytokine storm; elevation of the inflammatory mediators as erythrocyte sedimentation rate (ESR), interleukin (IL)-6, and C-reactive protein (CRP), which may cause severe disease with worse outcomes in COVID-19 patients." (PMID 36154838, 2022). "Our meta-analysis of five RCTs, in summary, testified to the following key findings: i) treatment with colchicine was associated with a significant reduction in the severity of COVID-19 ii) CRP levels were significantly lower in patients treated with colchicine compared to the control group." (PMID 35381033, 2022). "Together, our findings highlight sustained long-term alterations in monocyte and DC subsets after COVID-19, which could be linked to initial elevated circulating C-reactive protein (CRP) levels." (PMID 36685582, 2022). "We initially investigated the link between lung abnormality persistence by CT at the 180-day follow-up and known risk factors for COVID-19 severity, including male sex, the presence of comorbidities, and serum levels of CRP and S-specific IgG determined at the 60-day follow-up." (PMID 35256646, 2022).
COVID-19 (continued). "A survival analysis revealed that comorbidities, lymphocyte counts, platelet count, serum albumin, C-reactive protein level, and renal dysfunction may be risk factors in patients with COVID-19." (PMID 33762058, 2022). "High levels of IL-6, CRP, and hypertension could be considered as important risk factors for evaluating COVID-19 severity." (PMID 36010198, 2022). "Elevated serum CRP levels are negatively correlated with SpO2 and associated with aggravation in asymptomatic and mildly symptomatic cases, and mortality in severely-ill COVID-19 patients, demonstrating lung injury linked disease course." (PMID 35747751, 2022). "C-reactive protein may be studied as a convenient alternative, but its diagnostic accuracy is variable and often unsatisfactory even in identifying COVID-19 cases during triage." (PMID 35464745, 2022). "Moreover, clinical data from COVID-19 patients indicate that reduction of serum testosterone is negatively associated with levels of C-reactive protein (a marker of inflammation) and predictive of poor prognosis for COVID-19 patients." (PMID 35307018, 2022). "On the contrary, arterial thrombotic events were independently associated with less severe COVID-19 on admission, shorter duration of symptoms, lower CRP, better functional status on admission, higher comorbidity burden, established atherosclerotic disease, aspirin use, and other." (PMID 35230002, 2022). "Our finding of an association between delirium and raised CRP level suggests that inflammation may be involved in the pathophysiology of COVID-19-associated delirium." (PMID 35836717, 2022). "This may be mirrored by differences in underlying diseases since ICU-treated patients with COVID-19 may suffer from a more expressed infectious condition, which may be reflected by the generally higher levels of CRP in our cohort." (PMID 36555328, 2022). "Additionally, we found an indirect path between SE and teachers’ perceptions about the impact of COVID-19 through teachers’ perception of risk of contracting SARS-CoV-2 (CRP) and perception of the effectiveness of health measures (PEHM) (β = 0.03; p < 0.001)." (PMID 36141916, 2022). "Increased CRP levels also appear to be an independent risk factor for the development of acute respiratory failure (ARDS) in COVID-19 patients, which may also significantly affect the risk of death." (PMID 36078933, 2022). "In addition, the tracheal NLRP3 mRNA expression in both COVID-19 variants correlated with C reactive protein (CRP) and lactate dehydrogenase (LDH) in serum as well as with the age of patients." (PMID 36498845, 2022). "The model suggested LDL-C (p < 0.001), HDL (p < 0.001), TC (p < 0.001), TG (p < 0.001), free T3 (p < 0.001), free T4 (p < 0.001), TSH (p < 0.001), IL-6 (p < 0.001), Procalcitonin (p < 0.001), CRP (p < 0.001), and D-dimers (p = 0.021) as independent risk factors for COVID-19." (PMID 35637852, 2022). "Additionally, IL-6 and CRP have been associated with COVID-19 severity, with IL-6 being the most frequently reported cytokine elevated in COVID-19 associated CS." (PMID 35500008, 2022). "CRP mediated 32.7% of the total association between diabetes and severe COVID-19 outcome." (PMID 35967091, 2022). "CRP has been linked to disease progression and is an early indicator of severe COVID-19." (PMID 36562867, 2022). "Specifically, increased serum CRP levels, which indicate an inflammatory state and are associated with advanced age, indicate a poor prognosis and increased risk of mortality in elderly patients with COVID-19." (PMID 36089575, 2022). "Hs-CRP and ferritin were correlated with post-acute COVID-19 in patients recorded with the Alpha variant, while for the Delta variant, more biomarkers showed a significant correlation with this outcome, such as hs-CRP, RDW, NLR, SII, and WBC." (PMID 35741183, 2022).
COVID-19 (continued). "Similarly, in our study also, a CRP greater than 3 mg/L, ferritin greater than 388 ng/mL and procalcitonin greater than 0.10 ug/L were found to be associated with severe COVID-19 in the univariable model." (PMID 35566563, 2022). "Additionally, we found an indirect path between TS and teachers’ perceptions about the impact of COVID-19 through teachers’ perception of risk of contracting SARS-CoV-2 (CRP) and perception of the effectiveness of health measures (PEHM) (β = 0.02; p < 0.001)." (PMID 36141916, 2022). "In the combined model, CRP ≥7 mg/L with PROM latency ≥8.17 h at home showed higher diagnostic sensitivity and AUC than only CRP for initial assessing the risk of adverse neonatal complications in COVID-19 regional lockdowns (AUC, 0.714 vs. 0.534; sensitivity, 0.631 vs. 0.156)." (PMID 35463873, 2022). "However, in another study, increase in serum C-reactive protein was associated with poor results in COVID-19." (PMID 35168674, 2022). "Many studies suggest that CRP could be used to predict prognosis even before the onset of sickness as a biomarker for COVID-19 severity and that an increase in CRP is linked to a poor COVID-19 prognosis." (PMID 35958594, 2022). "Age, D-dimer, C-reactive protein, sequential organ failure assessment score and body temperature, decreasing albumin, and a history of diabetes were regarded as the major risk factors for COVID-19 severity." (PMID 36619998, 2022). "COVID-19 severity has, besides age and biological sex, been linked to an array of clinical parameters such as the level of soluble urokinase plasminogen activator receptor (suPAR), CRP, LDH, and viral load." (PMID 36685582, 2022). "As CRP is a well-known marker of COVID-19 severity, its independent association with OP development suggests that higher systemic inflammation on admission may be predictive of developing OP." (PMID 35898367, 2022). "The severity of COVID-19 appears to be related to an exacerbated immune response and events associated with vascular injury Several studies have documented the association between COVID-19 severity and circulating levels of C-reactive protein (CRP), interleukin-6, and D-dimer." (PMID 36163447, 2022). "Furthermore, in patients with diabetes mellitus, D-dimer has been reported as a significant predictor of COVID-19 mortality, while CRP has been associated with a severe course of COVID-19 in patients." (PMID 35746755, 2022). "In conclusion, while age, gender, ADMA, SDMA, L-NMMA, NLR, CRP, ferritin, D-dimer, and fibrinogen stood out as risk factors for COVID-19 severity in univariate analysis; only CRP, NLR, and L-NMMA were identified as independent risk factors through multivariate analysis." (PMID 36627978, 2022). "Circulating CRP and other inflammation mediators have been implicated in cardiovascular diseases and have also been investigated as independent predictors of prognosis in COVID-19." (PMID 35453906, 2022). "Model 2 tries to verify the indirect path between TS, JS, SE, EMO and teachers’ perception of COVID-19’s impact on relations through teachers’ risk perception of contracting SARS-CoV-2 (CRP) and perception of health measures effectiveness (PEHM) on social relationships at school (ISR)." (PMID 36141916, 2022). "At least in a retrospective evaluation, the FIASMA hydroxyzine was associated with a faster decrease in biological inflammatory markers associated with COVID-19-related mortality, including the neutrophil-to-lymphocyte ratio, the lymphocyte-to-C-reactive protein ratio, and circulating IL-6." (PMID 34608263, 2022). "Our data support the hypothesis that the damage to the lung caused in severe COVID-19 appears to result primarily from excessive CRP-mediated disposal of oxygen-depleted lung areas." (PMID 35407564, 2022). "COVID-19-related ACE2 SNP rs4646142 was associated with increased CRP (p < 0.001) level, and rs6632677 could also be associated with increased CRP (p = 0.004) and AGP (p < 0.001) levels." (PMID 36015068, 2022).